TSC2 (TSC complex subunit 2)
Diseases named in the same sentence as TSC2 in open-access papers (continued):
Sharing a sentence is not in itself a finding about the gene and the disease.
Parkinson disease (8 papers, 2012 to 2025). A progressive degenerative disorder of the central nervous system characterized by loss of dopamine producing neurons in the substantia nigra and the presence of Lewy bodies in the substantia nigra and locus coeruleus. "Previous work has shown that TIPE1/Oxi-beta can competitively bind to FBXW5 with tuberous sclerosis complex 2 (TSC2), increasing the stability of TSC2 and promoting excessive autophagy in Parkinson’s disease." (PMID 36118167, 2022). "Moreover, TIPE1 decreases mTOR phosphorylation by stabilizing TSC2 protein in a Parkinson's disease model." (PMID 31179241, 2019). "This protein binds to FBXW5, a tuberous sclerosis complex 2 (TSC2; a negative regulator of mTOR) binding receptor present in CUL4 E3 ligase complex, resulting in enhanced autophagy via activation of TSC2 in a Parkinson’s disease model." (PMID 30274259, 2018). "In a Parkinson’s disease model, TIPE1 binds to FBXW5, increasing autophagy through activation of TSC2." (PMID 29108244, 2017). "Interestingly, increased phosphorylation of the human TSC2 gene which inhibits its function in repressing TOR activity, has been found in the frontal cortex of Alzheimer's and Parkinson's disease patients." (PMID 23028662, 2012).
pulmonary lymphangioleiomyomatosis (8 papers, 2011 to 2023). "Here we show that lysosomal biogenesis is increased in TSC-associated renal tumors, pulmonary lymphangioleiomyomatosis, kidneys from Tsc2+/− mice, and TSC1/2-deficient cells via a TFEB-dependent mechanism." (PMID 34253722, 2021). "Lung-targeting LNPs were effectively used to introduce TSC2 mRNA into TSC2-null cells and suppress the mTOR pathway, resulting in improved control of tumor cell proliferation in a mouse model of pulmonary lymphangioleiomyomatosis." (PMID 36839944, 2023). "In addition, in a murine model of pulmonary lymphangioleiomyomatosis, increased PD-L1 expression was observed in Tsc2-null lesions." (PMID 31870441, 2019).
skin tumor (8 papers, 2008 to 2023). "We found that Gal-3 is elevated inTSC2 deficiency and mTORC1 activation, as Gal-3 levels were increased in human TSC skin tumors and TSC2-null skin tumor fibroblasts." (PMID 28695825, 2017). "Here, we test this combination using a well-established preclinical model of cutaneous tumorigenesis in TS, tsc2ang1 cells derived from a skin tumor from a mouse heterozygous for tsc2." (PMID 22765013, 2012). "Further supporting the second possibility, mosaicism has been frequently observed for TSC2 variants, including low-grade mosaicism with allele frequencies < 1% or variants only detected in skin tumor biopsies but not in blood or saliva." (PMID 31077186, 2019). "Finally, a study showing decreased expression of the TSC2 gene product, tuberin, in sporadic squamous and basal cell carcinomas suggests that mTOR inhibitors may be useful in treating these common skin cancers as well." (PMID 18226258, 2008).
angiosarcoma (7 papers, 2016 to 2023). A malignant tumor arising from the endothelial cells of the blood vessels. "In mice, homozygous disruption of Tsc1 or Tsc2 is lethal during embryogenesis, and heterozygous Tsc1+/− and Tsc2+/− mice develop renal cystadenomas, liver hemangiomas, and infrequently, paw angiosarcomas." (PMID 28695825, 2017).
cardiac hypertrophy (7 papers, 2013 to 2024). "The patients with cardiac hypertrophy had significantly higher levels of TR3 expression and corresponding lower levels of TSC2, which suggests that TR3 promoted the degradation of TSC2 and that the consequent induction of mTORC1 activity may be an important cause of cardiac hypertrophy." (PMID 23197407, 2013). "The genetic and pharmacological downregulation of class I HDACs blunts pathological cardiac hypertrophy by inhibiting TSC2-dependent mTOR signaling." (PMID 34540911, 2021). "The role of TR3 in the degradation of TSC2 was further assessed in AngII-treated mice and in samples from human patients with cardiac hypertrophy." (PMID 23197407, 2013). "Prior studies found that PKG activation, which phosphorylates TSC2 S1364 suppresses pressure-overload cardiac hypertrophy yet does not block cardiac hypertrophy caused by myocyte-specific Akt hyperactivation." (PMID 35288456, 2022). "TSC2 expression is upregulated in response to class 1 HDAC inhibition and is believed to be responsible for inhibiting cardiac hypertrophy." (PMID 39314240, 2024).
colon carcinoma (7 papers, 2014 to 2024). "Consistently, knockdown of TSC2 activates, whereas knockdown of mTOR inhibits, Notch signaling in the human colon cancer cell line LS174T." (PMID 25654764, 2015). "Our current in vivo findings further expand our earlier in vitro reports in which knockdown of TSC2 inhibited, whereas inhibition of mTOR increased, goblet cell differentiation in colon cancer cells." (PMID 25654764, 2015). "Several genes in the backbone of the CHIEF pathway were associated with survival, including PIK3CA for colon cancer and PRKAG2, STK11, and TSC2 for rectal cancer." (PMID 25541970, 2014). "In addition,the largest 40 nm Ag@TSC2 was shown to exhibit pronounced anticanceractivity against murine colon carcinoma (CT26) and murine mammarygland carcinoma (4T1) cells cultured as 2D and 3D tumor models andreduced toxicity against human HaCaT keratinocytes." (PMID 35344328, 2022).
developmental delay (7 papers, 2014 to 2024). "In infancy, up to 24 months of age, TSC2 pathogenic variant carriers are at higher risk for significant developmental delays." (PMID 38540392, 2024). "Early detection of the pathogenic TSC2 variant, followed by in utero administration of everolimus and early vigabatrin therapy, allowed the detection of a milder developmental delay of the proband." (PMID 37629066, 2023). "Finally, tuberous sclerosis complex 2 (TSC2) mutation was detected in one patient in the current study who presented with focal seizures at birth and later global developmental delay." (PMID 37628333, 2023). "However, our results shed new light on the relationship between Tsc2 haploinsufficiency and risk for early developmental delay both in sensorimotor development and in communication." (PMID 25165580, 2014). "TSC is associated with high instance of developmental delay and autistic phenotype; previous studies looking at early development and vocalizations in Tsc2+/− mice found that maternal heterozygosity at the Tsc2 locus is linked to changes in duration and number of calls per minute of pup USVs." (PMID 25165580, 2014). "Importantly, there is a proposed association between the type of TSC mutation (e.g., TSC1 or TSC2) and the risk of developmental delay, with a greater proportion of patients with TSC2 mutations suffering from moderate to severe delay as compared to patients with TSC1 mutations." (PMID 25165580, 2014).
leiomyosarcoma (7 papers, 2016 to 2025). An uncommon, aggressive malignant smooth muscle neoplasm, usually occurring in post-menopausal women. "Evidence supporting a direct role for the TSC complex in this cancer type is that the allelic loss of TSC2 in Eker mutant rats results in the spontaneous development of uterine leiomyosarcoma." (PMID 35201535, 2022). "A 48-year-old female with metastatic leiomyosarcoma and TSC2 mutation enrolled onto a mTOR inhibitor trial 2 days after her report was viewed in MatchMiner by the trial team." (PMID 36202909, 2022). "Owing to a germ-line mutation of the tuberous sclerosis gene 2 (Tsc2), Eker rats spontaneously develop various neoplasms, including leiomyosarcoma." (PMID 27716434, 2016). "In difficult cases, immunolabeling for more than one melanocytic marker and the demonstration of TSC2 mutations/alterations or TFE3 translocations might be helpful to differentiate PEComa from aberrant HMB-45-positive leiomyosarcoma." (PMID 31309284, 2020).
liver cancer (7 papers, 2021 to 2025). An epithelial or non-epithelial malignant neoplasm that arises from the liver. "Pifithrin-μ, an HSP70 inhibitor, synergized with sorafenib in the induction of ferroptosis in mTOR-activated liver cancer cells and suppression of TSC2-deficient hepatocarcinogenesis." (PMID 39863613, 2025). "We then assessed the impact of mTOR on sorafenib resistance in human liver cancer cells by using 3 TSC2-deficient cell lines (SNU886, SNU398 and Li7) and 3 TSC2 WT cell lines (HCCLM3, HepG2 and MHCC97H)." (PMID 39863613, 2025). "Pifithrin-μ in conjunction with sorafenib exerts the therapeutic potential in the treatment of TSC2-deficient human liver cancer cell-derived xenograft tumors and spontaneous mouse liver cancer." (PMID 39863613, 2025). "Targeting mTOR-CREB1-SESN3 axis may offer a promising therapeutic strategy to alleviate sorafenib resistance of TSC2 deficiency-associated mTOR-activated liver cancer." (PMID 39863613, 2025). "TSC2, a suppressor of mTOR, is inactivated in up to 20% of HBV-associated liver cancer." (PMID 39863613, 2025). "We demonstrated that regulation of pyrimidine synthesis by the β-catenin/AKT2 cascade still exists in MEFs, which lacks GS enzymatic activity, in S6K-depleted liver cancer cells, and in Tsc2 null cells where potential activation of β-catenin/AKT2 on S6K is disconnected." (PMID 36122209, 2022). "The TSC2 gene exhibited a positive correlation with C1GALT1 expression in pancreatic and liver cancers, while showing a negative correlation in colon, rectal, kidney‐clear cell, and melanoma cancers." (PMID 40548474, 2025).
lymphoma (7 papers, 2009 to 2023). A malignant (clonal) proliferation of B- lymphocytes or T- lymphocytes which involves the lymph nodes, bone marrow and/or extranodal sites. "To address whether inhibitors of translation elongation could also synergize with DNA damaging agents (e.g. Dxr), we tested the potential of four elongation inhibitors to modulate chemosensitivity in the Eμ-myc model harboring lymphomas with loss of Pten or Tsc2 or over-expressing Bcl-2 or eIF4E." (PMID 19412536, 2009). "While limited reports have documented a role for mTORC1 in promoting cell survival, knockout of TSC2 and activation of mTORC1 in a mouse model of lymphoma accelerated oncogenesis, suppressed tumor apoptosis, and decreased animal survival in vivo." (PMID 37507012, 2023). "In MYC-driven TSC2+/−Eμ-Myc lymphomas, DHX9 suppression had a straight lethal effect both ex vivo and in vivo." (PMID 28427210, 2017). "In TSC2+/−Eμ-Myc lymphomas, DHX9 suppression resulted in elevated levels of p21, PUMA, BAX, NOXA, BIM, c-MYC, and PLK2." (PMID 28427210, 2017). "The TSC2+/−Eμ-Myc lymphomas and INK4A−/− MEFs were therefore used as control lines for the remainder of this study." (PMID 28427210, 2017). "Systemic treatment of mice bearing Tsc2+/- Em-myc lymphomas (whose cells depend on Mcl-1 for survival) with obatoclax conferred a survival advantage compared to vehicle alone (median 31 days vs 22 days, respectively; p=0.003)." (PMID 26231047, 2015). "As well, HHT is able to block translation in mice bearing Tsc2+/−Eμ-Myc lymphomas as revealed by polysome analysis of tumors two hours following compound administration." (PMID 19412536, 2009). "To assess if MG132 would also antagonize the synergy we observed between elongation inhibitors and Dxr, we exposed Tsc2+/−Eμ-myc lymphomas to HHT or Rap with Dxr." (PMID 19412536, 2009). "As documented for Pten+/−Eμ-Myc lymphomas, inhibiting translation elongation in Tsc2+/−Eμ-Myc lymphomas also synergizes with Dxr to induce remissions in mice that lasted for up to 28 days." (PMID 19412536, 2009). "Tsc2+/−Eμ-Myc lymphomas were cultured ex vivo and exposed for various times to a concentration of compound sufficient to completely block global protein synthesis." (PMID 19412536, 2009). "For this purpose, we used Tsc2+/−Eμ-Myc lymphomas cultured ex vivo." (PMID 19412536, 2009).
neurocutaneous disorder (7 papers, 2009 to 2025). "Tuberous sclerosis complex (TSC), an inherited neurocutaneous disorder, is caused by variants in the TSC1 or TSC2 genes." (PMID 40745330, 2025). "Tuberous sclerosis complex (TSC) is a rare neurocutaneous disorder caused by heterozygous loss-of-function pathogenic variants in the tumour suppressor genes TSC1 and TSC2 encoding the tuberin and hamartin proteins, respectively." (PMID 39334956, 2024). "TSC is classified as a neurocutaneous syndrome, or a phakomatosis (birth mark) disorder, with an incidence of about 1 in 6000 births, associated with two separate genes located on either chromosome 9 (TSC1) or 16 (TSC2)." (PMID 38671997, 2024).
ovarian carcinoma (7 papers, 2014 to 2025). A malignant neoplasm originating from the surface ovarian epithelium. "Therefore, it is our hypothesis that FGFR1 and TSC2 might be associated with platinum resistance in ovarian cancer." (PMID 27677586, 2016). "TSC2 acts as a tumor suppressor in a variety of cancers (e.g. oral, lung and ovarian cancers), and the upregulation of EREG has been documented in a variety of cancers (e.g. colorectal, lung, pancreatic, oral and ovarian cancers) and in TSC patients." (PMID 24748662, 2014). "The hub genes (e.g., FGFR1 and TSC2) which have not been reported in previous literature might be potential platinum resistance-related genes in ovarian cancer." (PMID 27677586, 2016).
bladder cancer (6 papers, 2011 to 2024). "Mutations in genes concurrently with TSC1/TSC2, such as those frequently occurring in bladder cancers, will likely define the best treatment course." (PMID 28695825, 2017). "Using the TCGA database of cancers, the TSC2 loss-of-function expression signature, as well as levels of LGALS3, were associated with bladder cancers harboring TSC1/TSC2 inactivating mutations." (PMID 28695825, 2017). "A Tsc2/mTORC1 expression signature identified in Tsc2-deficient fibroblasts was also increased in bladder cancers with TSC1/TSC2 mutations in the TCGA database." (PMID 28695825, 2017). "This expression signature of TSC2 loss was increased in human bladder cancer with TSC1 or TSC2 mutation." (PMID 28695825, 2017). "TSC1 forms a complex with TSC2 and its mutations were found in a number of bladder cancer cases as well." (PMID 21283818, 2011). ", suggesting that Gal-3 may be an individual marker for bladder cancers containing inactivating mutations in TSC1 or TSC2." (PMID 28695825, 2017). "Bladder cancers with mutations in TSC1 or TSC2 also had higher levels of galectin-3, suggesting that other diseases linked with mutations in these genes may also result in increased production of galectin-3." (PMID 28695825, 2017). "Rapamycin and its analogs, rapalogs, cause partial responses in about 10% of RCC patients, and have been reported to have major benefit in occasional cases of bladder cancer and other cancer types with TSC1/TSC2 mutations." (PMID 37909334, 2023). "Data identified that in the low HER2 cohort and different ATM levels (high/low); ABL1, SMAD4, RB1 and PARP1 were significantly upregulated and AKT1, AKT2, TSC2, RPTOR and mTOR were significantly downregulated in bladder cancer." (PMID 36056635, 2022).
chordoma (6 papers, 2009 to 2023). Chordomas are rare malignant tumors arising from embryonic remnants of the notochord in axial skeleton. "Positive expression of phosphorylated AKT and TSC2 identified across chordoma samples indicates loss of tumor suppression stemming from activation of the PI3K pathway." (PMID 32733369, 2020). "The genes TSC1 and TSC2, being of the mTOR pathway, have raised the possibility that this pathway is implicated in intracellular signalling for oncogenesis in chordomas." (PMID 26391590, 2015). "Mutation of tumour suppressor genes TSC1 et TSC2 is seen in patients with chordomas associated with Tuberous Sclerosis." (PMID 26391590, 2015). "Further, the TSC2 variant observed in three Chinese chordoma cases was classified as DM by HGMD." (PMID 34070849, 2021). "Phosphorylated p70S6kinase expression (p-p70S6K), which lies downstream of TSC2 activation, was also identified; together, these data support the use of mTOR inhibitors to treat chordoma." (PMID 32733369, 2020). "This study focuses on determining if there is evidence for the activation of PI3K/AKT/TSC1/TSC2/mTOR signalling in chordomas in view of existing therapeutic inhibitors." (PMID 19401700, 2009). "Chordoma also occurs in association with TSC, an autosomal dominant neurocutaneous syndrome characterized by abnormal tissue growth in multiple organ systems caused by inactivating germline mutations in either TSC1 or TSC2." (PMID 34070849, 2021). "However, our finding that AKT is activated in over 90% of chordomas argues that the tumour suppressor genes, TSC2 and TSC1, in sporadic chordoma are likely to be ‘inactivated’ not as a result of loss of heterozygosity but rather by phosphorylation of TSC2, at threonine 1462, by p-AKT." (PMID 19401700, 2009). "More than 90% of the chordomas expressed p-AKT (Ser243), p-TSC2 (Thr1462), p-4E-BP1 (Thr70) and eIF-4E as assessed by IHC." (PMID 19401700, 2009). "Chordomas were positive for p-AKT (92%), p-TSC2 (96%), p-mTOR (27%), total mTOR (75%), p-p70S6K (62%), p-RPS6 (22%), p-4E-BP1 (96%) and eIF-4E (98%)." (PMID 19401700, 2009). "Interestingly, chordomas have been reported in patients with tuberous sclerosis complex (TSC), a multisystem syndrome due to TSC1 or TSC2 alterations resulting in constitutive mTOR hyperactivation, suggesting an etiological role of TSC gene alterations in chordomagenesis." (PMID 36983607, 2023).